HSPB8 (heat shock protein family B (small) member 8)
Description:
Involved in the chaperone-assisted selective autophagy (CASA), a crucial process for protein quality control, particularly in mechanical strained cells and tissues such as muscle. Displays temperature-dependent chaperone activity.
Synonyms: E2IG1; HSP22; H11; CMT2L; DHMN2; HMN2; HMN2A; HMND2; HSPB8-N1; HSPB8-N2; MFM13
Tractability: PROTAC: ubiquitination databases record sites on it.
Gene: Protein-coding gene on chromosome 12 (119,171,555 to 119,224,855, forward strand). Ensembl gene ENSG00000152137.
Subcellular location: Cytoplasm; Nucleus
Subcellular location (Human Protein Atlas): Cytosol; Nucleoplasm
Pathways (Reactome):
Cellular responses to stimuli: HSF1-dependent transactivation
Gene Ontology:
Molecular function: identical protein binding; protein binding; protein homodimerization activity; protein kinase activity
Biological process: cellular response to unfolded protein; positive regulation of aggrephagy
Cellular component: cytoplasm; cytosol; nucleoplasm; nucleus; protein folding chaperone complex
Genetic constraint (gnomAD): Loss-of-function variants: 8 observed, 15.3 expected, observed/expected ratio (o/e) 0.52, 90% interval 0.31 to 0.94. The upper end of that interval is the gene's LOEUF score, 0.94, which puts it in group 4 of 6, group 1 being the genes least tolerant of losing a copy. Missense variants: 237 observed, 260.49 expected, observed/expected ratio (o/e) 0.91, 90% interval 0.82 to 1.01. Synonymous variants: 99 observed, 100.36 expected, observed/expected ratio (o/e) 0.99, 90% interval 0.84 to 1.17.
Gene-disease validity (ClinGen):
ClinGen rates the evidence that HSPB8 causes each of these diseases.
neuronopathy, distal hereditary motor, autosomal dominant (autosomal dominant): Definitive. Autosomal dominant form of distal hereditary motor neuropathy.
Homologues: Orthologues: chimpanzee HSPB8 (100% identical), macaque HSPB8 (100% identical), guinea pig HSPB8 (97% identical), rat Hspb8 (95% identical), mouse Hspb8 (94% identical), rabbit HSPB8 (94% identical), pig HSPB8 (84% identical), dog HSPB8 (83% identical), tropical clawed frog hspb8 (66% identical), zebrafish hspb8 (56% identical), Drosophila melanogaster l(2)efl (29% identical), Drosophila melanogaster Hsp67Bc (24% identical), and 14 more. Paralogues in human: HSPB1 (37% identical), CRYAB (27% identical), CRYAA (23% identical), HSPB2 (23% identical), HSPB6 (22% identical), HSPB7 (21% identical), HSPB3 (17% identical), HSPB9 (12% identical).
Diseases named in the same sentence as HSPB8 in open-access papers:
HSPB8 is named in the same sentence as 122 diseases in open-access papers, as found by Europe PMC text mining. Sharing a sentence is not in itself a finding about the gene and the disease. The quoted sentences say what the papers report.
breast cancer (29 papers, 2012 to 2025). A primary or metastatic malignant neoplasm involving the breast. "Further, HSPB8 is linked to tamoxifen resistance in breast cancers and correlates with poor clinical outcome." (PMID 31273254, 2019). "HSPB8 was implicated in the mechanisms that modulate cell cycle and cell migration in breast cancer cells." (PMID 30446877, 2019). "Additionally, patients with breast cancer exhibiting upregulated expression of HSPB8 were associated with improved prognosis In our study, we found that HSPB8 were upregulated in exosomes secreted by breast cancer cells after hyperthermia." (PMID 37233869, 2023). "Furthermore, increased HSPB8 expression is linked to a worse outcome in ER+ breast cancer patients." (PMID 36359853, 2022). "Intriguingly, some reports suggest that HSP27 can amplify breast cancer progression by bolstering the SUMOylation of HSPB8, which in turn enhances its protein stability." (PMID 38213722, 2024). "Hsp27 induces the ubiquitination-like SUMOylation of Hspb8 to promote Hspb8 protein stability, which in turn supports breast cancer cell proliferation and metastasis." (PMID 39274941, 2024). "HSP22 (HSPB8, H11, HMN2, or E2IG1) has an estrogen-dependent expression in estrogen receptor-positive breast cancer cells and in some neuromuscular diseases." (PMID 36765939, 2023). "HSP27 induces SUMOylation of HSPB8 to promote HSPB8 expression, thereby endorsing proliferation and metastasis of breast cancer cells." (PMID 35928554, 2022). "Some studies demonstrated that HSPB8 is highly expressed in breast cancers, myeloma, ovarian cancer, gastric cancer, lung cancer, and cholangiocarcinoma where it increases cell proliferation, migration and tumorigenic activity." (PMID 36400750, 2022). "The knockdown of HspB8 expression inhibited in-vitro cell proliferation of breast cancer cells, while HspB8 overexpression enhanced cell proliferation and growth of breast cancer." (PMID 32927696, 2020). "E2­activated HSF1 was transcriptionally potent and several genes essential for breast cancer cells growth and/or ERα action, including HSPB8, LHX4, PRKCE, WWC1, and GREB1, were activated by E2 in a HSF1-dependent manner." (PMID 31614463, 2019). "H11/HspB8 has antiapoptotic activity in glioblastoma and breast cancer cells through cell-cycle regulation, potentially involving activation of the growth-associated transcription factor E2F and/or the cyclin-dependent kinase cdk4." (PMID 23056924, 2012). "The expression of HSPB8 in healthy breast tissue was higher than that in breast cancer tissues." (PMID 37233869, 2023). "In breast cancer, E2 could activate HSPB8, which promotes breast tumor cells growth by MAPK Signaling." (PMID 36937439, 2023). "The mTOR inhibitor (AZD8055) could inhibit the tamoxifen resistance in breast cancer cells by suppressing the expression of HSPB8." (PMID 35069935, 2022). "In particular, HSPB8 overexpression correlates to high risk of recurrence and metastasis in breast cancer, hepatocarcinoma, and head and neck squamous cell carcinoma, while low levels of HSPB8 are associated with negative prognosis in prostate cancer." (PMID 36400750, 2022). "The expression of HSPB8 is investigated to correlate with breast cancer progression." (PMID 35069935, 2022). "In corollary, a pro-proliferative role for HSPB8 has been reported in certain breast cancer models." (PMID 31273254, 2019). "For example, HSPB8 promotes tumor growth in breast cancer, lung cancer, ovarian cancer, and gastric cancer, while in other tumor types, such as hepatocarcinoma and prostate cancer, HSPB8 could repress tumorigenesis." (PMID 41190325, 2025). "In addition, HSPB8 is responsible for the rug resistance of breast cancer cells." (PMID 35069935, 2022). "Interestingly, studies have suggested that HspB8 might play an important role in estrogen response and breast cancer progression." (PMID 32927696, 2020).
breast cancer (continued). "Hsp27 was found to be expressed at high levels in breast cancer tissues and MCF-7 lines, upregulating HSPB8 by inducing the SUMOylation of HspB8, thereby facilitating the proliferation and metastasis of breast cancer cells." (PMID 38255948, 2024). "We then analyzed HSPB8 expression levels in different melanoma cell lines compared with human melanocytes and the MCF-7 breast cancer cells highly enriched in HSPB8." (PMID 36400750, 2022). "In triple-positive hormone-sensitive breast cancer cell lines (MCF-7), HSPB8 regulates the proliferation and reduction of the migratory ability for MCF-7 cells." (PMID 34235216, 2021). "Silencing of HSPB8 notably curtails MCF-7 cell proliferation and negates the proliferative impetus of 17β-estradiol, intimating a probable role for HSPB8 in the proliferative and migratory mechanisms governing breast cancer." (PMID 38213722, 2024). "In addition, the decreased expression of HSPB8 has been shown to lead to an increased number of cells resting in the G0/G1 phase and reduce the migratory ability of MCF-7 cells and thus is engaged in regulating cell cycle and cell migration in MCF-7 cells of breast cancer." (PMID 33456497, 2020).
distal hereditary motor neuropathy (15 papers, 2005 to 2025). "Mutations in the small heat shock protein B8 gene (HSPB8/HSP22) have been associated with distal hereditary motor neuropathy, Charcot–Marie–Tooth disease, and recently distal myopathy." (PMID 28780615, 2018). "Mutations in the α-crystallin domain of HSPB8 in humans leads to distal hereditary motor neuropathy, a disease characterized by the degenerative loss of motor neurons." (PMID 18671875, 2008). "Following the detection of the first HSPB8 mutations in distal hereditary motor neuropathy (dHMN), discovered simultaneously with HSPB1 mutations as cause on another dHMN, mutations in HSPB8 have also been linked to Charcot–Marie–Tooth (CMT) disease and muscle disease." (PMID 40243504, 2025). "Mutations in HSPB8 can cause distal hereditary motor neuropathy (dHMN), Charcot–Marie–Tooth (CMT) disease type 2L, or myopathy." (PMID 40243504, 2025). "It has also been found that HSPB8 hotspot mutations, K141E and K141N, cause distal hereditary motor neuropathy (dHMN) and Charcot–Marie–Tooth disease type 2F (CMT 2F), respectively with neural and muscular involvements." (PMID 30400176, 2018). "Similar to BAG3 and HSPB8, mutations in the genes coding for DNAJB2, HSPB1 and HSPB3 have been associated with distal hereditary motor neuropathy (dHMN), including Charcot–Marie–Tooth disease." (PMID 40757567, 2023). "Mutations in HSPB1, HSPB8, and HSPB3 are implicated in inherited peripheral neuropathies (IPNs), such as Charcot-Marie-Tooth disease type 2 (CMT2) and distal hereditary motor neuropathies (dHMN)." (PMID 35328016, 2022). "Mutations in HSPB8 are associated with distal hereditary motor neuropathy, Charcot-Marie-Tooth disease Type 2L (CMT2L; OMIM: 608673), and more recently with Neuronopathy, Distal Hereditary Motor, Type IIa (HMN2A; OMIM: 158590)." (PMID 34740639, 2022). "The majority of HSPB8 mutations have been identified in patients with Charcot–Marie–Tooth (CMT) type 2L, myopathy, and distal hereditary motor neuropathy (dHMN) type IIa." (PMID 33562660, 2021). "Despite their multifunctionality and ubiquitous expression, mutations in HSPB1 and HSPB8 affect specifically the peripheral nervous system causing the axonal form of Charcot-Marie-Tooth neuropathy (CMT2) and/or distal hereditary motor neuropathy (dHMN)." (PMID 32323160, 2020). "The first half of this paper will be focused on how mutations in HSPB1, HSPB3, and HSPB8 are linked to inherited peripheral neuropathies like Charcot-Marie-Tooth (CMT) disease and distal hereditary motor neuropathy (dHMN)." (PMID 32323160, 2020).
melanoma (13 papers, 2012 to 2026). A malignant, usually aggressive tumor composed of atypical, neoplastic melanocytes. "Taken together, these results show that the loss of HSPB8 contributes to melanoma transformation and its re-expression can reduce tumor aggressiveness acting on phenotype switching and migratory capacity, regardless of the mutational status of cells." (PMID 36400750, 2022). "The aim of this work was therefore to better clarify the role of HSPB8 in human melanoma with specific mutational status." (PMID 36400750, 2022). "In this study, we investigated HSPB8 protein expression and its role in melanoma cell lines carrying different mutations." (PMID 36400750, 2022). "In order to gain information on the molecular mechanism by which HSPB8 exerts its action in melanoma, we transiently transfected mutated forms of HSPB8 (HSPB8K141E and HSPB8K141N) in BLM and A375 cells." (PMID 36400750, 2022). "Collectively, our results suggest that HSPB8 has an antitumoral action in melanoma cells characterized by BRAF and NRAS mutations." (PMID 36400750, 2022). "Here, we elucidate the role of HSPB8 on cell growth, phenotype switching, and migration of human melanoma cell lines characterized by different driver mutations." (PMID 36400750, 2022). "Noteworthy is that, in human melanocytes, HSPB8 causes cell cycle arrest, while HSPB8 is silenced by aberrant DNA methylation in the majority of human melanomas." (PMID 33562660, 2021). "The first identified mutation in the HSPB8 gene in cancer cells causes a W51C substitution in the protein sequence and was reported in one melanoma line with an important transforming potential." (PMID 33562660, 2021). "Another HSPB8 anti-apoptotic mutation is the missense mutation P173H, found in human melanoma cell line MeWo." (PMID 33562660, 2021). "In melanoma cells with BRAF and NRAS mutations, HSPB8 plays an anti-tumor role by regulating processes such as autophagy." (PMID 41490177, 2026). "On the other hand, in melanoma cells, evidence is provided for an anti‐tumor role of heat shock protein B8 (HSPB8) through arresting cell growth, cell migration, and reversion of the epithelial‐mesenchymal transition." (PMID 38775220, 2024). "The stress-related protein HSPB8 was first discovered in human melanoma cells as a kinase of the H11 protein." (PMID 37404760, 2023). "WB analysis shows that HSPB8 protein level is variable among melanoma cell lines, but always lower than in MCF-7 cells." (PMID 36400750, 2022). "In conclusion, in melanoma HSPB8 counteracts proliferative and migratory cellular phenotype by enhancing inactive unprenylated RAS and autophagy." (PMID 36400750, 2022). "Collectively, these results demonstrate that HSPB8 acts both on mutated and wild-type NRAS proteins, and this event is crucial to explain antitumoral effects in melanoma cell lines." (PMID 36400750, 2022). "Conversely, other studies showed that HSPB8 is downregulated in leukemia and lymphoma, glioblastoma, hepatocarcinoma, prostate cancer, melanoma and its upregulation contributes to induce cell death and chemosensitivity generating an overall antitumoral effect." (PMID 36400750, 2022). "We have therefore demonstrated that HSPB8-induced autophagy is a crucial event that counteracts cell growth in melanoma." (PMID 36400750, 2022). "In fact, HSPB8 is highly expressed in melanoma cells and in primary melanoma tissues compared to melanocytes and its overexpression represents a marker of cellular transformation." (PMID 33562660, 2021). "Heat shock protein – HSPB8 is known to have aberrant kinase activity and is found silenced through altered DNA methylation in aggressive and drug-resistant melanoma." (PMID 33133131, 2020). "This is consistent with recent studies that demonstrated that overexpression of HSPB8 led to cell cycle arrest and apoptosis in certain melanoma models." (PMID 31273254, 2019).
melanoma (continued). "In other tumors (melanomas, prostate cancer (PC), Ewing’s sarcoma and leukemia), HSPB8 gene is methylated and poorly expressed." (PMID 28060751, 2017). "Collectively the data identify TAK1 as a central player in the H11/HspB8-induced growth arrest/death of melanoma cells and underscore the therapeutic promise of H11/HspB8." (PMID 23056924, 2012). "H11/HspB8 appears to be such a marker for Aza-C treatment of melanoma, with patients whose tumors have high levels of H11/HspB8 DNA methylation being seriously considered for demethylation therapy." (PMID 23056924, 2012). "Accordingly, H11/HspB8 expression is silenced through DNA methylation in a high proportion (77%) of melanoma tissues and cultures." (PMID 23056924, 2012). "Moreover, in melanoma cells with BRAF and NRAS mutations, HSPB8 exerts this role through the induction of autophagy, which counteracts cell growth." (PMID 38775220, 2024). "Therefore, our results demonstrate the relevance of HSPB8 in counteracting melanoma aggressiveness, via a decrease in RAS-prenylation that reduces the activity of this protein." (PMID 36400750, 2022). "In melanoma cell lines characterized by low HSPB8 levels, we demonstrated that the restoration of HSPB8 expression causes cell growth arrest, reversion of EMT (Epithelial-Mesenchymal Transition)-like phenotype switching and antimigratory effect, independently from the cell mutational status." (PMID 36400750, 2022). "Also, the studies of EMT-like reversion and cellular migration, the first event of an invasive process, confirmed the antitumoral effects of HSPB8 in melanoma." (PMID 36400750, 2022). "In addition, in A2058 and A375 melanoma cell lines, HSPB8 overexpression induced by 5-Aza-deoxy-cytidine treatment triggers apoptotic cell death, which correlates with the levels of HSPB8 DNA methylation." (PMID 33562660, 2021). "Recalling the HSPB8 pro-apoptotic activity in melanoma cells, it would be interesting to investigate if HSPB8 may be involved in the effects observed after GGA treatment." (PMID 33562660, 2021). "Indeed, the first studies on the role of HSPB8 in cancer were conducted in melanoma and were highly enigmatic." (PMID 33562660, 2021). "Indeed, PI3-K inhibition increased Aza-C-induced cell death in the melanoma lines that had low/moderate levels of H11/HspB8 methylation and thereby restored expression." (PMID 23056924, 2012). "Consequently, H11/HspB8 is silenced in a large proportion of melanoma tissues by aberrant DNA methylation (a CpG island is present at the 5′ UTR, 216 bp upstream of the transcription start site)." (PMID 23056924, 2012). "Thus, the HSPB8 expression might represent a promising factor for the onset and the progression of melanoma." (PMID 36400750, 2022). "Indeed, some investigators showed that HSPB8 is more expressed in melanoma cell lines and in patient biopsies compared to melanocytes and nevi, while others found that HSPB8 is downregulated by DNA hypermethylation in melanoma." (PMID 36400750, 2022). "More salient, are the latest findings about a role favoring cell invasion and migration in melanoma by HSP60, HSP27, and HSP105/110 as well as the promising anti‐melanoma role of HSPB8." (PMID 38775220, 2024). "We found that HSPB8 regulates RAS-prenylation both in NRAS-mutant and NRAS-wild-type melanoma cell lines, inhibiting the Akt/mTOR molecular pathway." (PMID 36400750, 2022). "We demonstrated that HSPB8 regulates the levels of the active prenylated form of NRAS in NRAS-mutant and NRAS-wild-type melanoma cell lines." (PMID 36400750, 2022). "The aim of this study was to evaluate the role of Small Heat Shock Protein B8 (HSPB8) on cell growth and migration of both BLM (BRAFwt/NRASQ61R) and A375 (BRAFV600E/NRASwt) human melanoma cell lines." (PMID 36400750, 2022).
melanoma (continued). "Therefore, we assessed whether the different HSPB8 protein levels observed in melanoma cells were due to regulation of transcription or translation/stability by analyzing its mRNA level by RT-qPCR demonstrating that HSPB8 mRNA levels recapitulate that of its protein levels found in WB." (PMID 36400750, 2022). "Furthermore, HSPB8 in melanoma cell lines and primary melanoma tissues is expressed at levels higher than normally found in melanocytes, and this could be related to the activation of growth-associated transcription factors, such as E2F and/or cyclin-dependent kinases (cdk), such as cdk4." (PMID 33562660, 2021). "Furthermore, we demonstrate that the HSPB8-mediated autophagy activation is a crucial event to prevent proliferation and migration of both BRAF- and NRAS-mutant melanoma." (PMID 36400750, 2022). "P173H HSPB8 loses its propensity to bind the transforming growth factor-beta-activated kinase 1 (TAK1), an interaction required to induce apoptosis, and it is thought to confer 5-Aza-deoxy-cytidine resistance to these melanoma cells." (PMID 33562660, 2021). "Expression analysis performed using real-time RT-PCR showed that HSPB8 mRNA is highly expressed in iPSCs, in BC cells (MCF-7) and in hepatocellular carcinoma (HepG2), while its expression is much lower in prostate cancer (PC) cells (PC3 and DU145 cells) and in melanoma cells (BML)." (PMID 28060751, 2017). "Indeed, one of the H11/HspB8 missense mutants, W51C, causes anchorage-independent growth and it overrides the death-inducing capacity of the wild-type H11/HspB8 through activation of the B-Raf/MEK/ERK pathway, which is a notorious contributor to melanoma development." (PMID 23056924, 2012).